TRPM3 (transient receptor potential cation channel subfamily M member 3)
Diseases named in the same sentence as TRPM3 in open-access papers (continued):
Sharing a sentence is not in itself a finding about the gene and the disease.
developmental delay (4 papers, 2023 to 2024). "This study presents a male pediatric patient with a pathogenic TRPM3 variant c.2509G>A [p.(Val837Met)], contributing to a complex clinical phenotype characterized by developmental delays, significant hypotonia, and neurological abnormalities." (PMID 39639951, 2024). "The patient presented with developmental delays, psychomotor impairments, and neurological abnormalities, with genetic testing revealing the pathogenic TRPM3 variant." (PMID 39639951, 2024). "The case presented highlights a 2 years patient, with a pathogenic variant c.2509G>A in the TRPM3 gene, translated as p.Val837Met, contributing to a complex clinical phenotype characterized by developmental delays, neurological abnormalities, and psychomotor impairments." (PMID 39639951, 2024).
glioblastoma (4 papers, 2016 to 2025). The most malignant astrocytic tumor (WHO grade IV). "TRPM3 is overexpressed in choroid plexus papillomas, glioblastoma multiforme, and clear cell renal cellcarcinoma (ccRCC), suggesting that TRPM3 has a tumor-promoting role." (PMID 27438705, 2016). "Within the transient receptor potential cation channels, TRPM3 gene expression was found increased in glioblastoma by 2.3-fold." (PMID 27716384, 2016). "It is currently unknown whether miR-204 expression actually increases as a result of TRPM3 overexpression in choroid plexus papillomas and glioblastoma multiforme." (PMID 27438705, 2016). "Within the shadowed columns, glioblastoma appears to have the highest number of modified ion-channel genes (namely: FXYD5, KCNE3, KCNE4, CLIC1, TRPM3)." (PMID 27716384, 2016). "Altered expression of TRPM3 has been observed in glioblastoma but not in Wilms tumors." (PMID 34624066, 2021).
cataract (3 papers, 2014 to 2025). Partial or complete opacity of the crystalline lens of one or both eyes that decreases visual acuity and eventually results in blindness. "Previously, we have shown that Trpm3-null mice fail to develop early-onset cataract, whereas knock-in of a human cataract-associated mutation in Trpm3 (p.I65M) elicits early-onset, progressive cataract with lens calcification and pro-fibrotic immune responses." (PMID 38334649, 2024). "Mutations of TRPM3 have been associated with the development of neuronal disorders and cataracts." (PMID 40305282, 2025). "Despite the role of TRPM3 in heat detection by sensory neurons, neither Trpm3 deficiency nor Trpm3 mutation appeared to impact the reversal of cold cataracts in the lens." (PMID 38334649, 2024).
melanoma (3 papers, 2013 to 2020). A malignant, usually aggressive tumor composed of atypical, neoplastic melanocytes. "Despite its shared sequence homology with TRPM1 (~ 69% amino acid similarity, 57% amino acid identity), TRPM3 (melastatin-2) is not directly associated with melanocyte differentiation or melanoma." (PMID 32070426, 2020). "Nonetheless, TRPM3/miR-204 levels are lower in nevi compared with melanoma samples." (PMID 28445987, 2017). "Downregulation of TRPM1/melastatin mRNA in primary malignant melanoma is a prognostic marker for metastasis; however, the pathobiologic role of TRPM3 in endometrial carcinoma remains largely unknown." (PMID 24321270, 2013).
rheumatoid arthritis (3 papers, 2010 to 2021). A chronic, systemic autoimmune disorder characterized by inflammation in the synovial membranes and articular surfaces. "Stimulation of TRPM3 also inhibited secretory activity in fibroblast-like synoviocytes from rheumatoid arthritis patients, as TRPM3 agonist inhibited hyaloronan release." (PMID 33732703, 2021). "The objective of this study was to investigate the potential relevance of Transient Receptor Potential Melastatin 3 (TRPM3) channel to fibroblast-like synoviocytes (FLSs) of patients with rheumatoid arthritis." (PMID 20525329, 2010). "The data suggest expression and function of TRPM3 channels in cells that line the synovium of joints of patients suffering from rheumatoid arthritis." (PMID 20525329, 2010). "Secretion of hyaluronan, which contributes adversely in rheumatoid arthritis, was suppressed by pregnenolone sulphate in FLSs from patients and the effect was blocked by anti-TRPM3 antibody." (PMID 20525329, 2010). "According to research, TRP channels have become drug targets for the treatment of RA as there are multiple TRP channels in rheumatoid arthritis synovial fibroblasts, including TRPV1, TRPA1, TRPC5, TRPM3, TRPM7, and TRPM8." (PMID 30792744, 2019).
systemic sclerosis (3 papers, 2019 to 2022). A chronic disorder, possibly autoimmune, marked by excessive production of collagen which results in hardening and thickening of body tissues. "TRPM3 potentiates glutamatergic transmission at cerebellar Purkinje neurons and is involved in insulin secretion, whereas TRPM3 gene polymorphisms may be associated with systemic sclerosis." (PMID 31011981, 2019).
Arthritis (2 papers, 2018 to 2022). Inflammation of a joint. "TRPM3 is implicated in the development of heat hyperalgesia that commonly accompanies inflammatory pain states, such as arthritis." (PMID 35496916, 2022). "In summary, the current data suggests that agonism of TRPC5, TRPM3, TRPM8, and TRPV2 may help ameliorate or prevent arthritis, while antagonism of TRPM7 and TRPV4 may have a similar effect." (PMID 30326593, 2018). "Therefore, similar to the current literature concerning TRPM3’s role in arthritis, further studies are warranted to determine whether TRPV4 serves a protective or pro-inflammatory role in arthritis development." (PMID 30326593, 2018).
autism spectrum disorder (2 papers, 2020 to 2021). A spectrum of developmental disorders that includes autism, and Asperger syndrome. "Although it is not yet known whether these PregS dependent phenomena occur via TRPM3 or other receptors, a truncation mutation of TRPM3 is associated with autism spectrum disorder when coupled to a mutation of the dmd gene, frequently associated with muscular dystrophy." (PMID 32238415, 2020).
autosomal dominant polycystic kidney disease (2 papers, 2019 to 2025). Autosomal dominant form of polycystic kidney disease. "In autosomal dominant polycystic kidney disease (ADPKD), a minority of patients lack functional TRPP2, and pregnenolone sulfate is not likely to have therapeutic value in the absence of the TRPM3/TRPP2-dependent channel." (PMID 30883612, 2019).
bipolar disorder (2 papers, 2021). A disorder of the brain that causes unusual shifts in mood, energy, activity levels and the ability to carry out day-to-day tasks. "Interestingly, genetic variants within the TRPM3 gene have been associated with abnormal postpartum behaviour in the porcine infanticide model and hippocampal Trpm3 expression is altered in a mouse model with serotonergic abnormalities and with possible relevance for bipolar disorder." (PMID 33219387, 2021). "Fittingly, it was also shown that TRPM3 expression was altered in a mouse model of bipolar disorder due to serotonin depletion, thereby supporting the idea that TRPM3 may regulate mood conditions." (PMID 33732703, 2021).
cognitive deficits (2 papers, 2024 to 2025). "Behavioral abnormalities and cognitive impairment aligned with previous reports of TRPM3-related neurodevelopmental disorders." (PMID 39639951, 2024). "Cognitive impairments represent a significant aspect of TRPM3-related disorders, affecting various domains of intellectual functioning." (PMID 39639951, 2024).
colitis (2 papers, 2024 to 2025). Inflammation of the colon. "In a recent study on a mouse model of DSS-induced colitis, TRPM3 has been identified in colon-projecting dorsal root ganglion (DRG) neurons." (PMID 38731999, 2024). "Additionally, TRPM3 levels were found to be increased in DRG neurons of mice with colitis." (PMID 38731999, 2024). "The search terms used were "Transient Receptor Potential Channels", "TRP channels", "TRPV1", "TRPA1", "TRPV4", "TRPV2", "TRPM2", "TRPM3", "TRPM7", "TRPM8", "TRPC3", "colitis", "inflammatory bowel disease", "IBD", "ulcerative colitis", "Crohn Disease"." (PMID 41096659, 2025). "Further studies are required, including other TRP channels (e.g., TRPM2, TRPM3, TRPM8, TRPV2), which have demonstrated beneficial or negative effects on intestinal inflammation in animal models of colitis, to confirm/refute the severity of these effects in humans." (PMID 38731999, 2024). "However, according to existing data on other TRP channels and the observed effects in animal colitis models, there is a need to study positive/negative events associated with TRPM2, TRPM3, TRPM8, and TRPV2 channels in humans." (PMID 38731999, 2024).
diabetes (2 papers, 2020 to 2022). "American Indians have a high prevalence of both type 2 diabetes and impaired glucose tolerance, and one could speculate that carriers of the TRPM3 SNV may benefit from using preferentially these medications for diabetes prevention." (PMID 35665752, 2022). "This drug does not cause impaired glucose tolerance, pre-diabetes, or diabetes, suggesting that TRPM3 is not essential for insulin secretion." (PMID 32168890, 2020). "Among the four genes (PHIP, TRPM3, SPTY2D1 and TSPO) associated with fasting insulin and combined into a genetic risk score, we showed that carriers of insulin increasing risk alleles had higher odds of developing diabetes and impaired fasting glucose at follow-up." (PMID 35665752, 2022).
mood disorder (2 papers, 2021 to 2023). A cognitive disorder a disturbance in which the person's mood is hypothesized to be the main underlying feature. "Beyond TRPM2, recent research highlights TRPM3 as a potential player in the development of mood and anxiety disorders, with specific mention of post-partum mood disorders." (PMID 36902145, 2023).
prostate carcinoma (2 papers, 2017 to 2023). A carcinoma that arises from epithelial cells of the prostate gland. "In RPE cells, we suppose that cAMP leads to the activation of protein kinase A, which in turn opens L-type Ca2+ (e.g., CACNA1A: 3.85 mFPKM; CACNA1A: 2.63 mFPKM) or TRP channels (e.g., TRPM3: 1.71 mFPKM; TRPM4: 7.76 mFPKM), as shown in epidermal melanocytes and prostate cancer cells." (PMID 29249973, 2017).
Anophthalmia (1 paper, 2014). Absence of the globe or eyeball. "In mice, disruption of Trpm3 results in a mild pupilary phenotype, whereas, Pax6-deficiency results in a severe eye phenotype characterized by aphakia, microphthalmia and anophthalmia." (PMID 25090642, 2014).
Astigmatism (1 paper, 2024). A type of refraction error associated with abnormal curvatures on the anterior and/or posterior surface of the cornea. "As mentioned in the presented case, visual disturbances, including astigmatism and hypermetropia, underscore the multisystem nature of TRPM3." (PMID 39639951, 2024).
astrocytoma (1 paper, 2021). "In NHAs and astrocytoma cell lines, the expression of miRNA-204-5p was related to that of TRPM3, suggesting that miRNA-204-5p and TRPM3 might be subjected to similar regulatory mechanisms." (PMID 34723710, 2021).
Ataxia (1 paper, 2023). Ataxia refers to impaired coordination of voluntary muscle movement. "We highlight a cerebellar phenotype (ataxia or severe hypotonia, nystagmus or abnormal oculomotricity, and cerebellar atrophy) in more than half of the patients as a novel feature of the TRPM3-linked disease pattern." (PMID 36648066, 2023).
Autoimmunity (1 paper, 2024). The occurrence of an immune reaction against the organism's own cells or tissues. "Dysfunction of TRPM3 in natural killer (NK) cells, characterized by reduced calcium flux, has been observed in ME/CFS and PCS patients, suggesting a role in ineffective pathogen clearance and potential virus persistence and autoimmunity development." (PMID 38970055, 2024).
Azoospermia (1 paper, 2022). Absence of any measurable level of sperm,whereby spermatozoa cannot be observed even after centrifugation of the semen pellet. "Meanwhile, miR-22-5p, the impresser of TRPM3, was found to be upregulated in testicular tissue from patients with the non-obstructive azoospermia." (PMID 35634321, 2022).
congenital stationary night blindness (1 paper, 2017). "The closest relative of TRPM3 is TRPM1, which is expressed in retinal ON-bipolar cells, and its mutations in humans cause congenital stationary night blindness." (PMID 28829742, 2017).
Corneal astigmatism (1 paper, 2023). "By using a GWAS approach, SNPs near TJP2, PCBP3, CADM2, and TRPM3 were identified to be associated with myopia or refractive errors, and HMG20A and PPP2R2B were associated with axial length and corneal astigmatism, respectively." (PMID 37449273, 2023).
cyst (1 paper, 2025). A sac-like closed membranous structure that may be empty or contain fluid or amorphous material. "A comparison of findings from IBMX-driven cystic kidneys clearly demonstrated that TRPM3 inhibition with isosakuranetin sensitized the kidneys to IBMX-induced cyst formation, increasing both cyst area and number." (PMID 39922884, 2025). "Our results in FSK-driven tubule expansion are compatible with that idea and the findings in IBMX-driven tubule expansion provide strong evidence that TRPM3 modulation impacts cyst formation via a pathway that involves cAMP signaling." (PMID 39922884, 2025). "Having established that TRPM3 inhibitors promote cyst development, we tested whether TRPM3 activators would have the opposite effect." (PMID 39922884, 2025). "It would, nevertheless, be very useful to discover whether TRPM3 activation makes polycystin mutants relatively resistant to forskolin-induced cyst formation, ideally restoring it to the lower sensitivity of wild-type." (PMID 39922884, 2025). "If TRPM3 activators antagonize cyst formation, this may be therapeutically useful whatever the molecular link between TRPM3 and cyst formation." (PMID 39922884, 2025). "It would also be very useful to discover whether TRPM3 activation reduces forskolin-induced cyst formation in PC2 mutants as well as in the more common PC1 mutants." (PMID 39922884, 2025). "Our results show that the cyst-promoting effect of cAMP elevation on developing mouse kidneys is exacerbated by co-incubation with any of a range of TRPM3 inhibitors, but is attenuated by co-incubation with TRPM3 activators." (PMID 39922884, 2025). "We therefore examined the effect of pharmacological activators and inhibitors of TRPM3 on cyst formation in cultured mouse kidney rudiments exposed to a range of concentrations of forskolin, a cAMP-elevating drug commonly used experimentally to induce cysts in cultured kidneys." (PMID 39922884, 2025). "We therefore used these to test whether inhibition of TRPM3 would promote cyst formation." (PMID 39922884, 2025). "We found that TRPM3 inhibitors (isosakuranetin, primidone, diclofenac) increased cyst formation, while TRPM3 activators (CIM0216 and nifedipine) greatly reduced cyst formation and reduced the sensitivity of kidneys to forskolin." (PMID 39922884, 2025). "In E12.5 kidneys treated with the TRPM3 inhibitor, isosakuranetin, along with a range of IBMX concentrations, cyst formation was observed at all tested IBMX concentrations from 0.5 to 50 μM." (PMID 39922884, 2025). "To establish a baseline for normalizing the effect of TRPM3 modulation on cyst formation in kidneys with blocked cAMP degradation by IBMX, we first generated a plot of cyst formation in kidneys treated with varying concentrations (0.5–50 μM) IBMX alone for 5 days." (PMID 39922884, 2025). "Consistent with our hypothesis, TRPM3 blockade by isosakuranetin, primidone and diclofenac (red/brown lines) increased number and areas of cysts, while TRPM3 activation by CIM0216 and nifedipine (green lines) led to a marked attenuation of the cyst-promoting activity of FSK." (PMID 39922884, 2025).
cystitis (1 paper, 2021). Inflammation of the urinary bladder. "We also do not exclude that the increased functionality of TRPM3 may contribute to bladder pain associated with cystitis and that TRPM3 antagonism may cause relieve in bladder pain patients." (PMID 35008533, 2021). "After induction of cystitis by injection of cyclophosphamide, we observed a robust increase of the functional responses to agonists of TRPM3, TRPV1, and TRPA1 in bladder-innervating DRG neurons." (PMID 35008533, 2021). "In mice with CYP-induced cystitis, the proportion of WGA-AF555-labeled neurons responding to TRPM3, TRPV1, and TRPA1 agonists was significantly higher than in sham treated animals (p = 0.002, p < 10−6, and p = 0.02, respectively)." (PMID 35008533, 2021). "To detect changes in TRPM3 channel activity during bladder inflammation, we performed calcium imaging on retrogradely labeled DRG neurons isolated from control mice and mice with CYP-induced cystitis." (PMID 35008533, 2021). "Our findings further indicate that, both under normal circumstances and during cystitis, TRPM3 does not play a critical role in the process of bladder filling and voiding." (PMID 35008533, 2021). "In vivo measurements in wild type and TRPM3-deficient mice did not reveal a crucial role for TRPM3 in bladder filling/voiding, both in control conditions and in a model of cyclophosphamide (CYP)-induced cystitis." (PMID 35008533, 2021).
Dysmenorrhea (1 paper, 2025). Pain during menstruation that interferes with daily activities. "As endometrial CYP17A1 levels are increased in patients with severe dysmenorrhea, we could hypothesise that DHEA and TRPM3 might play a key role in the pain perception during painful menstruation." (PMID 41154581, 2025).
endometrial carcinoma (1 paper, 2013). A malignant tumor arising from the epithelium that lines the cavity of the uterine body. "Whether TRPM3 and miR-204 could cooperate with each other in the pathogenesis of human endometrial carcinoma remains unknown but is an intriguing and biologically important question." (PMID 24321270, 2013).
endometriosis (1 paper, 2025). The growth of functional endometrial tissue in anatomic sites outside the uterine body. "Additional expression studies are required to further pinpoint the potential role of TRPM3 and neurosteroids in endometriosis-associated pain and to explore the downstream signaling cascade." (PMID 41154581, 2025). "Taken together, these data indicate a potential contribution of steroidogenesis and TRPM3 in endometriosis-associated pain." (PMID 41154581, 2025). "The prospective ExPAND study proposes the neurosteroids pregnenolone sulphate (PS) and dehydroepiandrosterone sulphate (DHEAS) as potential contributors to endometriosis-associated pain, due to their agonistic action at the pain-related ion channel TRPM3." (PMID 41154581, 2025). "It is important to note that, in addition to TRPM3, other receptors may also contribute to endometriosis-associated pain, including members of the tropomyosin receptor kinase family (TrkA, TrkB, and TrkC) as well as the p75 neurotrophin receptor (p75NTR)." (PMID 41154581, 2025). "Given the inflammatory and steroid-dependent character of endometriosis, we hypothesised that these neurosteroids might contribute to endometriosis-associated pain through activation of TRPM3 in sensory nerve endings that innervate the lesions." (PMID 41154581, 2025). "Although the endometrium is poorly innervated by sensory neurons, TRPM3 expression is reported in whole-tissue biopsies from both controls and endometriosis patients." (PMID 41154581, 2025). "Interestingly, the endogenous neurosteroids pregnenolone sulphate (PS), DHEA, and DHEA-sulphate (DHEAS), which are presumably involved in endometriosis’ pathophysiology, are also direct agonists of TRPM3." (PMID 41154581, 2025).